IL10 (interleukin 10)
Diseases named in the same sentence as IL10 in open-access papers (continued):
Sharing a sentence is not in itself a finding about the gene and the disease.
lumbar disc herniation (2 papers, 2020 to 2023). "LXA4 diminishes pain in the non-compressive lumbar disc herniation model by inhibiting production of pro-inflammatory cytokines (TNF-α, and IL-1β) and upregulating IL-10 and transforming growth factor-beta (TGF-β)." (PMID 37388729, 2023).
lung squamous cell carcinoma (2 papers, 2024 to 2025). "Elevated IL-10, IL-13, and TERT levels and reduced MCP-1/MCAF levels are associated with lung squamous cell carcinoma." (PMID 40292253, 2025). "Our study suggested that IL-10 could act as a protective factor against lung squamous cell carcinoma, adding to the complex narrative surrounding this cytokine." (PMID 39132165, 2024).
mammary adenocarcinoma (2 papers, 2020). "We used a multivariate principal component analysis applied to analyze the joint behavior of serum concentrations of IFN-γ, IL-2, IL-10 and IL-4, during the different phases of tumor immunoediting, in CBi/L mice challenged with M-406 mammary adenocarcinoma." (PMID 33312693, 2020).
myeloid leukemia (2 papers, 2014 to 2022). A clonal proliferation of myeloid cells and their precursors in the bone marrow, peripheral blood, and spleen. "In our study, IL-4 could induce the expression of M2 markers including IL-10, TGF-β, and CD163 as well as some chemokines including CCL-17 and CCL-22 in human myeloid leukemia mononuclear THP-1 cells." (PMID 35996149, 2022).
narcolepsy (2 papers, 2018 to 2022). A sleep disorder characterized by a tendency for excessive sleepiness during the day which occurs even after adequate sleep in the nighttime. "In addition, narcolepsy patients’ plasma and CSF levels of IL-8 (chemotactic factor) and IL-10 (anti-inflammatory cytokine) are unchanged when compared to controls." (PMID 36358399, 2022). "IL10RB–IFNAR1 (the IL-10 and interferon receptor gene region), ZNF365 (that encodes the transcription factor ZNF365), and P2RY11 (encodes P2Y purinoceptor 11) and the chemokine receptor CCR1–CCR3 region are all linked to narcolepsy." (PMID 36358399, 2022).
nephrotoxicity (2 papers, 2021 to 2024). Toxicity that causes injury to the kidney or damages its function. "Pioglitazone reduced the mRNA levels of pro-inflammatory cytokines (IL-6 and TNF-α) and increased the mRNA levels of anti-inflammatory cytokines (IL-4 and IL-10) in an in vitro model of calcium oxalate monohydrate-induced nephrotoxicity." (PMID 39621679, 2024).
neuritis (2 papers, 2017 to 2024). A neuropathy arising from inflammation of one or more nerves. "This neuritis is one of the very rare examples of a “pro-inflammatory function” of generally anti-inflammatory IL-10 and is caused by an IL-10-dependent ICAM-1 upregulation which triggers macrophage influx." (PMID 29179723, 2017). "Second, mice on C57BL/6 background, transgenically expressing IL-10 under the control of the promotor of the vitelliform macular dystrophy 2 (VMD2) gene mutated in macular degeneration, spontaneously develop neuritis within 10 to 20 weeks of age." (PMID 29179723, 2017).
Neurogenic bladder (2 papers, 2014 to 2023). A type of bladder dysfunction caused by neurologic damage. "Yet another study indicated that the L. reuteri RC-14 exerted downregulation of IL-10 in the patients with neurogenic bladder of spinal cord injury." (PMID 25759833, 2014). "Some case reports have measured inflammatory biomarkers when treating with Lactobacillus rhamnosus GR-1 and Lactobacillus reuteri RC-14, resulting in attenuated expression of TNF-α, IL-6, IL-8, IL-10 and IL-12 (p70) in the neurogenic bladder of SCI patients with UTIs." (PMID 37291666, 2023).
NK/T-cell lymphoma (2 papers, 2015 to 2022). "Analysis of 12 single nucleotide polymorphisms (SNPs) in IL-10, TNF-α, lymphotoxin-α (LTA), and CTLA-4 genes was performed for 125 patients with NK/T-cell lymphoma and 300 healthy controls by PCR-ligase detection reactions." (PMID 26108796, 2015). "In this study, our results showed that LTA +252 A > G polymorphism is associated with a 2.9-fold risk of NK/T-cell lymphoma, but other polymorphisms of the IL-10, TNF-α, and CTLA-4 genes are not." (PMID 26108796, 2015).
oral candidiasis (2 papers, 2022 to 2024). Infection of the mucosal lining of the mouth with the fungus Candida albicans. "In the diabetic population, an increase in IL-10 or a decrease in IFN-γ may be associated with an increased risk of oral candidiasis." (PMID 36443718, 2022). "Rani M. mentioned the levels of IL-10 are generally higher in diabetic patients with oral candidiasis, but the levels are lower when Candida albicans antigens are applied as peripheral blood stimulants." (PMID 36443718, 2022). "According to the results of the present study, with a rise in IL-10, the probability of developing oral candidiasis in the diabetic group increases by about 40%." (PMID 36443718, 2022). "An increase in interleukin-10 by 40% and a decrease in IFN-γ by 6% can increase oral candidiasis prevalence among diabetic patients." (PMID 36443718, 2022). "The likelihood of developing oral candidiasis increases as the level of IFN-γ decreases and the level of IL-10 increases." (PMID 36443718, 2022). "The study aimed to correlate serum interleukin 10 (IL-10) and interferon-gamma cytokines (IFN-γ) with oral candidiasis in T2DM." (PMID 36443718, 2022).
oral cavity cancer (2 papers, 2012 to 2014). A primary or metastatic malignant neoplasm involving the oral cavity. "The main reason for these could be the inherent differences in tumours from different sites of the head and neck where patients with oral cavity cancers are more likely to have undetectable levels of IL-10 compared to other sub-sites." (PMID 25153698, 2014).
oral mucositis (2 papers, 2023 to 2026). Inflammation of the mucous membranes of any of the structures in the mouth. "In an oral mucositis experimental model, administration of AZIL dramatically lowered TNF-α and IL-1β levels while boosting the levels of the anti-inflammatory cytokine IL-10." (PMID 37908315, 2023).
orchitis (2 papers, 2021 to 2024). Inflammation of one or both testes due to viral or bacterial infections. "Animals subjected to LPS were found to have severe orchitis, as evidenced by increased oxidative stress and surging inflammatory mediators (TNF-α, IL-1β, and IL-6), with declined IL-10 levels." (PMID 39845795, 2024). "Orchitis may be induced by discrepancies in the inflammatory and anti-inflammatory cytokine levels in testicular cells, including TNF-α, interleukin (IL)-1β, (IL-6), and IL-10." (PMID 39845795, 2024).
otitis media with effusion (2 papers, 2025 to 2026). Otitis media associated with accumulation of fluid in the middle ear. "The analysis of cytokine levels in adults with OME, including IL-2, IL-4, IL-5, IL-10, IL-12, and interferon (IFN)-gamma, reveals distinct patterns associated with otitis media with effusion (OME) and allergic conditions." (PMID 40497981, 2025).
Ovarian cyst (2 papers, 2015 to 2025). The presence of one or more cysts of the ovary. "Further research could include animals with higher BCS or with ovarian cysts to compare their IL-10 FF level." (PMID 41373524, 2025).
papilloma (2 papers, 2012 to 2017). A benign epithelial neoplasm that projects above the surrounding epithelial surface and consists of villous or arborescent outgrowths of fibrovascular stroma. "In fact, IL-10 deficient mice were more sensitive to DMBA/TPA induced papilloma." (PMID 23176085, 2012). "As a possible mechanism, the dominance of Th2-like cytokine (IL-4 and IL-10) responses and decreased secretion of IFN-γ were reported by peripheral blood mononuclear cells (PBMC) exposed to autologous papilloma tissues in patients with RRP." (PMID 28298239, 2017).
Peritoneal Fibrosis (2 papers, 2023 to 2024). Disorder characterized by a wide range of structural changes in PERITONEUM, resulting from fibrogenic or inflammatory processes. "One study showed that overexpression of IL-10 significantly reduced infiltration of CD68+ peritoneal macrophages and thickening of the fibrous peritoneum in rats, resulting in notable relief from peritoneal fibrosis." (PMID 39749340, 2024).
pituitary tumor (2 papers, 2021 to 2022). A benign or malignant neoplasm affecting the pituitary gland. "As early as 1995, studies showed that expressed interleukin-10 (IL-10) affects pituitary tumor cells of mice and isolated mouse pituitary glands." (PMID 36009467, 2022). "The study showed that a high IL-10 expression in pituitary tumor tissues was associated with an increased invasiveness of non-functioning PA; thus, IL-10 levels in peripheral blood can be used as a diagnostic marker for invasive non-functioning PA." (PMID 36009467, 2022).
plague (2 papers, 2007 to 2009). Plague is a severe bacterial infection caused by the gram-negative bacterium Yersinia pestis. "V-mediated IL-10 secretion is thought to be involved in plague pathogenicity by preventing the release, to serum, of proinflammatory cytokines, such as TNF-α and IFN-γ, postinfection, and by subsequently suppressing the innate immune responses to plague infection." (PMID 17640293, 2007). "LcrV triggers the release of IL-10 by host immune cells and suppresses proinflammatory cytokines such as TNF-α and INF-γ as well as innate defense mechanisms required to combat the pathogenesis of plague." (PMID 19701461, 2009). "The presumably high levels of IL-10 release following vaccination do not appear to be desirable for effective plague vaccination." (PMID 17640293, 2007).
pleural tuberculosis (2 papers, 2012 to 2024). Inflammation of the pleura secondary to an infection with Mycobacterium tuberculosis. "The application of tuberculous pleurisy mouse models will aid in identifying its underlying mechanisms and the studying the regulatory role of IL-10 in this disease." (PMID 39003443, 2024). "However, an association between IL-10 promoter polymorphisms at −819 and −592 sites with elevated IL-10 levels in pleural tuberculosis has been reported." (PMID 22509293, 2012). "It is widely accepted that IL-10, IL-22 and IL-26 inhibit the pathological progression of tuberculous pleurisy by suppressing inflammatory responses while promoting local immune responses." (PMID 39003443, 2024). "The exsiting research indicates that regardless of the specific immune cell type producing IL-10 in the microenvironment of tuberculous pleurisy, it plays a crucial role in dampening inflammation." (PMID 39003443, 2024).
postherpetic neuralgia (2 papers, 2024 to 2025). "The results of multi-factor Logistic regression analysis showed that age, CD4+/CD8+ ratio, Treg cell ratio, IL-6, TNF-α, and IL-10 were the independent risk factors for postherpetic neuralgia (p < 0.05)." (PMID 40606470, 2025). "Additionally, higher levels of interleukin (IL)-10 (95%CI = 0.973-0.998, p = 0.019) and IL-12p70 (95%CI = 0.973-0.997, p = 0.013) were associated with a lower risk of postherpetic neuralgia." (PMID 39385821, 2024).
postmenopausal osteoporosis (2 papers, 2019 to 2021). Metabolic disorder associated with fractures of the femoral neck, vertebrae, and distal forearm. "Our data suggested that the specific SNP combination of TGF-β1 (−509) and IL-10 (+1927) may act as a predictive factor for postmenopausal osteoporosis in Taiwanese women." (PMID 34207210, 2021).
pregnancy hypertension (2 papers, 2021 to 2023). "We found that GROA and IL-9 exhibited causal relationships with pregnancy hypertension, while interleukin-10 (IL-10) and hepatocyte growth factor (HGF) demonstrated causal relationships with PE." (PMID 38362587, 2023).
Pruritus (2 papers, 2022 to 2024). Pruritus is an itch or a sensation that makes a person want to scratch. "However, IL-10 expression was shown to be increased in CSU lesions and a CSU mouse model overexpressing IL-10 exhibited increased pruritus and increased IL-2, IL-4, and IFN-γ expression, driven by JAK/STAT signaling." (PMID 35872776, 2022).
rapid-eye-movement sleep behavior disorders (2 papers, 2023). "Plasma TNF-α and IL-10 were significantly elevated in REM sleep behavior disorder (RBD) (prodromal to PD) relative to age-matched controls and to decreased IL-6/IL-10 and IL-8/IL-10 levels." (PMID 37085942, 2023).
Respiratory syncytial virus infection (2 papers, 2014 to 2022). "Respiratory syncytial virus infection increases Mif MRNA expression in mouse macrophages and inhibition of MIF with ISO-1 (small molecule inhibitor) inhibits RSV-induced release of TNF, MCP-1 and IL-10." (PMID 36110852, 2022).
retinal detachment (2 papers, 2012 to 2013). An eye emergency condition which may lead to blindness if left untreated. "Most cytokines concentrations (IL-2, IL-6, IL-8, IL-10, IL-17, TNF-α, IFN-γ, VEGF) were not statistically significant different compared to the rhegmatogenous retinal detachment control group except IL-1β." (PMID 23049699, 2012).
retinitis pigmentosa (2 papers, 2020 to 2021). Retinitis pigmentosa (RP) is an inherited retinal dystrophy leading to progressive loss of the photoreceptors and retinal pigment epithelium and resulting in blindness usually after several decades. "It is also known that, together with IL-10, it is able to suppress several pro-inflammatory cytokines, and in mouse models of retinitis pigmentosa, application of TGF-β1 was able to protect degenerating cones and save vision." (PMID 33925714, 2021).
retinopathy of prematurity (2 papers, 2008 to 2020). A bilateral retinopathy characterized by neovascularization, scarring, retinal detachment, and eventually blindness. "This suggests that anti-IL-10 immunotherapy may be an attractive avenue for the treatment of retinopathy of prematurity." (PMID 18852882, 2008).
rhabdomyolysis (2 papers, 2021 to 2022). Necrosis or disintegration of skeletal muscle often followed by myoglobinuria. "On the day of the rhabdomyolysis onset, the patient had fever with increased IL-6, IL-10, and PCT." (PMID 35313994, 2022).
rhabdomyosarcoma (2 papers, 2022 to 2025). A rare aggressive malignant mesenchymal neoplasm arising from skeletal muscle. "Our present study indicated that APN deficiency conferred a higher frequency of CD8+IFN-γ+ T cells in the spleen and lymph nodes, as well as higher levels of IFN-γ, perforin, and TNF-α and lower levels of IL-10 in the serum of rhabdomyosarcoma-bearing mice." (PMID 35530361, 2022). "Subsequently, we determined the protein levels of IFN-γ, perforin, TNF-α, and IL-10 in the serum of both rhabdomyosarcoma-bearing wild-type and APN−/− mice." (PMID 35530361, 2022). "On the contrary, the attenuation of chemerin action in rhabdomyosarcoma (RMS) led to increased production of pro-inflammatory cytokines such as IL-1β, IL-6, interleukin 10 (IL-10), and TNF-α." (PMID 40076482, 2025). "As expected, compared to wild-type mice with rhabdomyosarcoma, the serum levels of IFN-γ, perforin and TNF-α of rhabdomyosarcoma-bearing APN−/− mice were much higher, whereas the level of IL-10 in serum was much lower." (PMID 35530361, 2022). "In the present study, we observed a lower expression of p-STAT3 in CD8+ T cells isolated from rhabdomyosarcoma-bearing APN−/− mice, which was also accompanied by higher IFN-γ and lower IL-10 in the serum." (PMID 35530361, 2022).
spinal tuberculosis (2 papers, 2023 to 2024). "Elevated levels of TGF-β1 and IL-10 in the tissues affected by spinal tuberculosis can lower the immune system’s ability to kill Mycobacterium tuberculosis." (PMID 38572322, 2024). "Interleukin-10 (IL-10) plays a role in reducing the inflammatory response by interacting with other inflammatory factors, thereby impacting the progression of spinal tuberculosis." (PMID 38572322, 2024). "A promoter polymorphism in IL-10 (rs1800871) was associated with increased CRP and ESR levels in patients with spinal tuberculosis, a complication of Mycobacterium tuberculosis infection." (PMID 37238156, 2023). "Based on our findings, monitoring IL-10 and TGF-β1 levels in older patients with spinal tuberculosis may be useful for evaluating the patient’s immune function and disease progression." (PMID 38572322, 2024).
spondyloarthritis (2 papers, 2018 to 2021). "HLA-B27/human β2m transgenic rats (B27-rats) develop an inflammatory disorder resembling spondyloarthritis (SpA) with dysregulated IL-10/IL-17 production by regulatory T cells (Treg)." (PMID 34271972, 2021).
squamous intraepithelial lesion (2 papers, 2018 to 2025). "The overexpression of IL-10 can lead to the transformation of squamous intraepithelial lesions (SIL) to CC." (PMID 39856040, 2025).
Strabismus (2 papers, 2017 to 2021). A misalignment of the eyes so that the visual axes deviate from bifoveal fixation. "We found the expression of INF-γ, IL-10, IL-12p70, and IL-17A in tears of strabismus patients, which were no significantly higher than those of normal subjects, while IL-6 and TNF-α were statistically significant." (PMID 34659636, 2021).
synucleinopathy (2 papers, 2021 to 2022). A neurodegenerative disease that is characterized by the abnormal accumulation of aggregates of alpha-synuclein protein in neurons, nerve fibers or glial cells. "In conclusion, we have revealed an unexpected detrimental outcome following the expression of Il-10 and vIl-10 in mouse models of synucleinopathy." (PMID 33741985, 2021). "To test the effect of Il-10 signaling on synucleinopathy, we delivered AAV-Il-10 and AAV-green fluorescent protein (GFP) into the spinal cords of neonatal homozygous M83+/+ mice." (PMID 33741985, 2021). "Contrary to our expectations, we uncovered a detrimental effect of intraspinal Il-10 expression in our synucleinopathy models." (PMID 33741985, 2021). "Taken together, our study points to a novel aspect of immune signaling in synucleinopathies, whereby Il-10 conditioning can exacerbate the pathologic landscape through a combination of cell-autonomous and non-cell-autonomous means, as shown in other models of neurodegenerative diseases." (PMID 33741985, 2021). "Based on the hypothesis that chronic neuroinflammation underlies the etiology of synucleinopathy and extracellular αSyn has DAMP-like properties, anti-inflammatory mediators such as Il-10 would be expected to ameliorate αSyn proteinopathy by dampening neuroinflammation." (PMID 33741985, 2021). "It is noteworthy that Il-10 itself did not increase microgliosis in the brain or spinal cord or promoted synucleinopathy in the seeded model." (PMID 33741985, 2021).
T cell deficiency (2 papers, 2015 to 2017). "While the prime focus of this work was to examine the role of PKCζ in CB T-cell development-specific functional phenotype, studies on IL-12 and IL-10 were conducted to provide a comparison with the T-cell deficiency per se." (PMID 28159873, 2017). "The increasing IL-10+ B-cell frequencies with increasing FT3 levels reported in this study may reflect compensation for the relative IL-10+ T cell deficiency." (PMID 26016954, 2015).
Takotsubo cardiomyopathy (2 papers, 2021). "The levels of IL-10 which is an anti-inflammatory cytokine rise due to the abundance of macrophages surrounding the myocardial tissue subjected to very high wall stress in Takotsubo syndrome." (PMID 34095448, 2021). "Thus, there is likely to be more IL-10 released in Takotsubo syndrome compared to AMI patients due to the pro-inflammatory nature of Takotsubo syndrome which needs to be counteracted as part of the mechanism of homeostasis." (PMID 34095448, 2021). "IL-2, IL-4, IL-10, IFN-γ and TNF-α at admission were shown to be significantly higher in patients with acute Takotsubo syndrome compared to patients with AMI, conversely, IL-6 was much higher in AMI patients." (PMID 34095448, 2021). "In addition, IL-10 likely prevents cardiomyocyte apoptosis via TNF-α, accounting for the functional recovery in patients with Takotsubo syndrome." (PMID 34095448, 2021).